MTOR (mechanistic target of rapamycin kinase)
Diseases named in the same sentence as MTOR in open-access papers (continued):
Sharing a sentence is not in itself a finding about the gene and the disease.
glioma (continued). "In IDH1 mutant glioma, PI3K/mammalian target of rapamycin (mTOR) suppression led to decreased production of the oncometabolite 2-hydroxyglutarate (2HG), and this is associated with improved survival." (PMID 35163279, 2022). "In glioma, through its PI3K/AKT/mTOR signaling pathway regulation, TRAM2 is able to enhance tumor cells migration, invasion, proliferation, and EMT." (PMID 36618348, 2022). "BYSL also reportedly promotes glioma/glioblastoma growth via the GSK-3β/β-catenin and AKT/mTOR pathways." (PMID 35508466, 2022). "Inhibiting PI3K/Akt/mTOR, Shh, Wnt/β-Catenin, and HIF-1α can reduce the migration ability and drug resistance of tumor cells to improve the prognosis of glioma." (PMID 35935338, 2022). "PI3K/Akt/mTOR, including the endogenous inhibitors PTEN, TSC1/2, and PHLPP, is one of the most common and most characterized malfunction pathways in glioma." (PMID 35785151, 2022). "Increased oncogenic signaling via the PI3K/Akt/mTOR and MAPK/ERK pathways, along with increased reactive oxygen species (ROS) production have been shown to contribute to the metabolic reprogramming of glioma cells, leading to constitutive HIF signaling." (PMID 36115843, 2022). "Western blot analysis showed that overexpression of CAMK1D downregulated p-Akt, p-mTOR, and p-P70S6K, and decreased p-Akt/Akt, p-mTOR/mTOR, and p-P70S6K/P70S6K ratios in glioma cells." (PMID 35494053, 2022). "The most affected signaling pathways in glioma cells involve tyrosine kinase receptors and their downstream pathways, such as the phosphatidylinositol 3-kinases (PI3K/AKT/mTOR) and mitogen-activated protein kinase pathways (MAPK)." (PMID 35628161, 2022). "The combination of mTOR inhibitors and targeted inhibition of Ras and PDGFR α is still a possible way to treat glioma." (PMID 35785151, 2022). "The recent research shown that the combined with inhibitors of PI3K/Akt/mTOR and SHH is obviously better therapeutic effect than the single inhibitor for glioma." (PMID 35935338, 2022). "Mechanistically, miR-3591-3p can directly target CBLB and MAPK1 in macrophages and glioma cells, respectively, and further activate the JAK2/PI3K/AKT/mTOR, JAK2/STAT3, and MAPK signaling pathways." (PMID 36085418, 2022). "Gene Ontology and KEGG database revealed the involvement of these miRNAs in the control of PI3K/AKT signaling pathway, MTOR signaling pathway, regulation of actin cytoskeleton, axon guidance, MAPK signaling, glioma and gap junction." (PMID 35602517, 2022). "Overall, GALNT2 facilitates the malignant characteristics of glioma by influencing the O-glycosylation and phosphorylation of EGFR and the subsequent downstream PI3K/Akt/mTOR axis." (PMID 35935338, 2022). "In summary, we found that exosomal miR-3591-3p can facilitate macrophage polarization toward the M2 phenotype by targeting CBLB to activate the JAK2/PI3K/Akt/mTOR and STAT3 pathways, which in turn promotes glioma progression." (PMID 36085418, 2022). "Curzerene, as a traditional Chinese medicine extract, can inhibit the malignant progression of glioma by downregulating GSTA4, p‐mTOR, MMP9, and other signals." (PMID 35048517, 2022). "In our study, it was found that HIF1α of glioma cells under hypoxia treatment entered the nucleus and the expression increased significantly, and the changes of AKT, mTOR, and ERK1/2 under silvestrol treatment were rescued." (PMID 35677890, 2022).
glioma (continued). "The most affected signaling pathways in glioma cells involve RTKs and their downstream pathways, such as the phosphatidylinositol 3-kinases (PI3K/AKT/mTOR) and mitogen-activated protein kinase pathways (MAPK)." (PMID 36555334, 2022). "In contrast, hsa-miR-129-5p has been shown to inhibit the cell cycle and induce apoptosis in glioma cell lines through inhibition of NOTCH1 and mTOR signaling." (PMID 33926464, 2021). "AMPK-mediated inhibition of the mammalian target of rapamycin (mTOR) signaling decreases protein synthesis, making IDH mutant glioma cells vulnerable to synthetic lethality through inhibition of B cell lymphoma-extra large (Bcl-xL)." (PMID 34073734, 2021). "Few studies have reported different therapeutic targets, such as mTOR, EGFR, and VEGFR, for the treatment of glioma." (PMID 34838021, 2021). "The reduction of autophagy was attributed to the activation of the PI3K/Akt/mTOR signaling pathway; however, more detailed mechanisms of CRNDE in glioma needed to be revealed." (PMID 34454479, 2021). "Studies have shown that NLGN3 induces phosphorylations of multiple RTKs as well as downstream PI3K-Akt-mTOR and Erk-MAPK cascades, responsible for glioma cell growth and proliferation." (PMID 34373757, 2021). "Overexpression of RIOK3 has opposite effects on the proliferation, migration, invasion of glioma cells, and the AKT/mTOR signal transduction pathway." (PMID 34138931, 2021). "We identified a complex consisting of BYSL, RIOK2, and mTOR, and observed co-localization and positive correlations between BYSL and RIOK2 in glioma cells and tissues." (PMID 33628587, 2021). "Flovokawain (chalcone) inhibits cell proliferation in the U87, T98 and U251 glioma cell lines via activating autophagy and subsequent senescence mediated by ER stress; moreover, it also inactivated the AKT/mTOR pathway." (PMID 33525678, 2021). "As a dual inhibitor of PI3K/mTOR, GNE-477 exerts an obvious antitumor effect on glioma cells, prompting us to explore its possible mechanism." (PMID 34381355, 2021). "However, the relation between decorin, EMT and c-Met/Akt/mTOR axis remains unclear in glioma cells." (PMID 34386415, 2021). "Our analysis of clinical data from the TCGA database indicated that mTOR, STAT3, and CDK6 are collectively hyper-expressed in both low-grade glioma and GBM cohorts." (PMID 34572040, 2021). "For the first time, we propose the role of TSN in the inhibition of the viability and metastasis of glioma cells through the promotion of induced apoptosis and inhibition of the PI3K/Akt/mTOR pathway." (PMID 34530814, 2021). "Because BYSL, RIOK2, and mTOR existed in the same complex, we next identified the role of BYSL in regulating RIOK2, AKT, and mTOR signaling in glioma cells." (PMID 33628587, 2021). "Another in vitro study reported that in glioma-initiating cells, the repression of PI3K/AKT/mechanistic target of rapamycin (mTOR) signaling and sonic hedgehog signaling markedly reduced cell survival, renewal capacity and tumorigenic potential." (PMID 33876384, 2021). "In in vitro experiments, taxifolin inhibited mTOR and PI3K activity in five different glioma cell lines." (PMID 34462635, 2021). "The expression and activity of the AKT/mTOR signaling molecules were determined by Western blot analysis, and the role of BYSL in glioma growth was confirmed in an orthotopic xenograft model." (PMID 33628587, 2021). "Importantly, the value of the MEN1611 therapy may be general for the treatment of brain tumors and not be limited to Shh-type MBs alone, because selective inhibition of the PI3K/AKT/mTOR pathway appears to be a promising strategy also in Wnt-type MBs, in Group 3 MBs and in gliomas." (PMID 34395258, 2021). "In a similar study, NVP-BEZ235, an inhibitor of the PI3K/mTOR pathway, was shown to induce autophagy in glioma LN229, U87, U373 and SF763 cells in vitro and enhanced survival in glioma xenograft models." (PMID 33525678, 2021).
glioma (continued). "It has been confirmed that LncRNAs can function as molecular signaling mediators to regulate glioma phenotypes through mediating the expression of genes in NEAT1-WNT/β catenin 27 and CRNDE- mTOR signaling pathway." (PMID 34093827, 2021). "It had been reported that through inactivating PI3K/AKT/mTOR signaling pathway, FK228 sensitizes human glioma cells to TMZ." (PMID 33663509, 2021). "The Nrf2 knockdown decreases the proliferation of glioma cells via ATP depletion, 5′ AMP-stimulated PK activation and subsequently blocks the mTOR pathway." (PMID 34199460, 2021). "In gliomas, GSK-3β is downregulated; its overexpression inhibits angiogenesis and tumor growth by upregulating the β-catenin and mTOR/p70S6K1 pathways, and also restores cell differentiation." (PMID 34887392, 2021). "The FGFR2-INA fusion was previously reported in low grade gliomas that drove oncogenesis via MAPK and PI3K/mTOR pathway activation." (PMID 33710807, 2021). "We also further evaluated a range of autophagy-related proteins, including mTOR, p-mTOR, ATG5, ATG12 and Beclin-1 in glioma cells." (PMID 34683892, 2021). "The EGFR or PTEN alteration induces continuous stimulation of the PI3K/Akt/mTOR pathway and increases activated AKT levels in glioma cells, thereby leading to tumorigenesis and resistance to cancer therapy." (PMID 34199460, 2021). "First, XL388 is significantly more potent than other known Akt-mTOR inhibitors (LY294002, perifosine and rapamycin) in killing glioma cells." (PMID 33159013, 2020). "In conclusion, our results demonstrate that LRRC4, which is frequently deregulated in glioma, directly binds to DEPTOR and induces its degradation to activate mTOR, thereby inhibiting cell autophagy." (PMID 32372061, 2020). "In this way, we were surer that ARG inhibited glioma cell proliferation and growth through the AKT/mTOR pathway." (PMID 33015162, 2020). "In this particular study, TTP inversely correlated with IL-13 levels in glioma tissues and TTP inhibited the growth, migration, and invasion of glioma cells through downregulation of IL-13 and attenuation of the PI3K/Akt/mTOR pathway." (PMID 32545247, 2020). "Guo found that 5-methoxypsoralen inhibits the expression and phosphorylation of PI3K, Akt, and mTOR in human glioma cells, thereby completely down-regulating the expression and activation of the PI3K/Akt/mTOR signaling pathway." (PMID 33344242, 2020). "In a word, lncRNA GAS5 suppressed cisplatin-induced excessive autophagy and thus increased cisplatin sensitivity in an mTOR-independent manner, suggesting that lncRNA GAS5 was a potential and promising target for overcoming glioma chemoresistance." (PMID 33029125, 2020). "A more intense hyperphosphorylation (activation) of AKT and mTOR has been reported in grade-III and -IV gliomas than in low-grade gliomas as related with a poorer prognosis in glioblastoma patients." (PMID 32707662, 2020). "The report from Chen indicated that PD-L1 modulated immune cell infiltration in glioma microenvironment (TME) and served as signaling protein control multiple pathways including STAT3, PI3K/AKT/mTOR, Ras/ERKsignaling pathways." (PMID 32061256, 2020). "Second, restoring Akt-mTOR activation, by caAkt1, only partially attenuated XL388-induced glioma cell death." (PMID 33159013, 2020). "Further, LncRNA THOR (Lnc-THOR) silencing inhibited glioma cell survival by depleting MAGEA6 and inhibiting mTOR signaling." (PMID 33159013, 2020). "The secreted soluble neuroligin-3 can act as a mitogen for the glioma, inducing focal adhesion kinase (FAK), phosphoinositide 3-kinase (PI3K)-mTOR pathway, expression of neuroligin-3 and other synapse genes, leading to the proliferation of the glioma cells." (PMID 31884567, 2020).
glioma (continued). "Our results suggest that the Ras/Raf/MEK/ERK and PI3K/Akt/mTOR pathways play a key role in the pathogenesis of grade III and IV gliomas." (PMID 33171577, 2020). "Mechanistically, NLGN3 can induce Fos expression, activate PI3K, Akt, and mTOR, and further induce NLGN3 expression in glioma cells." (PMID 33187183, 2020). "Here in the present study, we provided evidence that JMJD2A was up-regulated in human glioma tissues and JMJD2A promoted glioma cell growth by promoting the activation of the Akt-mTOR pathway." (PMID 32256210, 2020). "We thought ARG inhibited the proliferation of glioma cells by inducing autophagy and apoptosis through the AKT/mTOR pathway." (PMID 33015162, 2020). "Simultaneous activation of several key receptor tyrosine kinase (RTKs) induces sustained and profound activation of downstream cascades, including PI3K-Akt-mTOR and Erk-MAPK, promoting glioma cell progression." (PMID 31794427, 2019). "Modulation of G0S2 expression affects GBM responses to IR treatments in vitro and in vivo through mTOR/S6K/RNF168/53BP1-regulated DNA repair, suggesting G0S2 as a potential mediator of glioma responses to IR." (PMID 30953555, 2019). "We elucidated that triptolide induced G2/M-phase arrest, apoptosis, and autophagy in glioma cells by activating the ROS/JNK and inhibiting Akt/mTOR signaling pathways." (PMID 31157167, 2019). "We elucidated that celastrol induced G2/M-phase arrest, apoptosis, and autophagy in glioma cells by modulating the ROS/JNK and Akt/mTOR signaling pathways." (PMID 31053160, 2019). "These cascades, including PI3K-Akt-mTOR and Erk-MAPK signaling, shall promote glioma tumorigenesis and progression." (PMID 31794427, 2019). "A recent paper showed that Tan IIA inhibited the viability of glioma cells and induce apoptosis and autophagy possibly via inactivation of the PI3K/Akt/mTOR signal pathway." (PMID 31754613, 2019). "In an exploration of the mechanism of SRT2183-dependent autophagic cell death in glioma cell lines, we found the AKT/mTOR pathway phosphorylation, which has negative regulatory effects on autophagy." (PMID 31319814, 2019). "In conclusion, our study showed that the antitumor effects of celastrol in glioma cells are related to G2/M phase arrest and the triggering of autophagy and apoptosis via the activation of ROS/JNK signaling and blocking of the Akt/mTOR signaling pathway." (PMID 31053160, 2019). "This is exemplified by BEZ235, a phosphatidylinositol-3-kinase (PI3K)/mammalian target of rapamycin (mTOR) inhibitor that blocks AKT phosphorylation (Thr308/Ser473) and can prevent breast, glioma, and non-small-cell lung cancer growth." (PMID 31210839, 2019). "Remarkably, the hyper-activation of mTOR signaling in transgenic mice results in a marked expansion of the SVZ stem cell compartment and subsequent glioma development." (PMID 31387280, 2019). "Inhibition of mTOR, a downstream molecule of the PI3 kinase/PTEN/AKT pathway, promoted the response of glioma cells to EGFR-TKIs in vitro." (PMID 31284441, 2019). "A number of studies have demonstrated that key pathways which regulate major metabolic functions, such as PI3K/Akt/mTOR, MAPK/MNK, and AMPK pathways, are deregulated in cancers including in gliomas." (PMID 31795417, 2019). "This readily identified major pathways with well-established roles in glioma growth as well as clear connections with PI3K and mTOR signaling downstream of RTK activation." (PMID 31420543, 2019). "Here, we present evidence that in human GBMs, the dual PI3K/mTOR inhibitor dactolisib inhibits cell viability, induces apoptosis, and enhances the RT+TMZ treatment effect in glioma cell lines." (PMID 29416647, 2018).
glioma (continued). "To gain insight into the molecular mechanism by which Prucalopride regulated glioma cell proliferation and migration, we thus tested the effect of Prucalopride on the activation of AKT/mTOR signaling pathway in U251 cells using western blot assay." (PMID 29866060, 2018). "As increasing evidence showing that AKT/mTOR pathway is often connected with proliferation and apoptosis of glioma cells, we chose to evaluate the potential role of TGF-β1 on the classical AKT/mTOR pathway." (PMID 29467947, 2018). "On the other hand, it has been demonstrated that berberine induced autophagy in glioma cells through the activation of AMPK, with subsequent inactivation of mTOR and an increase in the levels of phosphorylated ULK1." (PMID 30486451, 2018). "The U-118 glioma cell line, in which the MGMT gene is hypermethylated, is more sensitive to TMZ when the PI3K/AKT/mTOR and ERK/MAPK signaling pathways are inhibited." (PMID 30486451, 2018). "Imatinib induced cell death by autophagy in U87MG and U373-MG human glioma cells, inhibiting the AKT/mTOR pathway and activating ERK1/2." (PMID 30486451, 2018). "Before and after radiotherapy significant differences were described in metabolites, cells rapidly turn to OXPHOS inhibiting mTOR and HK2 in glioma cell line, as a model system." (PMID 30574020, 2018). "Nowadays, the association between TMZ and autophagy has been clarified, TMZ induces the sustained inhibition of AKT-mTOR, and in turn produces an induction of autophagy in glioma, indicating TMZ-induced autophagy depends on mTOR signaling." (PMID 30326943, 2018). "It was found that inhibiting mTOR or Akt decreased the pool of CD133+ cells, which exhibit CSC properties in specific cancers, including gliomas." (PMID 30323898, 2018). "In our study, we examined the effects of DS in a panel of genetically diverse glioma cells and GIC, DS showed inhibition of PI3K/mTOR signaling in 9 glioma lines and 22 GIC lines." (PMID 28423515, 2017). "Our result revealed that the protein levels of IGF1R, IRS1, mTOR, and Bcl‐2 were increased in TMZ‐resistant glioma cells (U87‐TR and SF295‐TR) compared with TMZ‐sensitive glioma cells (U87 and SF295)." (PMID 28064447, 2017). "CPZ has also been shown to inhibit cell-cycle progression in rat glioma C6 cells by inducing p21Waf/Cip1/Egr1 expression and to induce autophagic cell death by inhibiting the AKT/mTOR pathway in human glioma U87-MG cells." (PMID 28455961, 2017). "Rapalogs and newly developed mTOR inhibitors are being tested with recurrent and therapy resistant malignancies, especially in AML and glioma patients." (PMID 28578659, 2017). "In this study, we studied a brain-penetrant dual PI3K/mTOR inhibitor, DS-7423, that can inhibit PI3K/mTOR signaling in a diverse panel of GBM and glioma initiating cell (GIC) lines at a brain-achievable concentration." (PMID 28423515, 2017). "We explored the candidate mechanisms in Lenti-RASD1 glioma cells by an intracellular signaling array that can simultaneously reflect several important signaling cascades, e.g., MAPK, mTOR, and AKT." (PMID 28600528, 2017). "Neurofibromin regulates glioma cell growth through the AKT/mTOR pathway, such that Nf1−/− astrocytes exhibit AKT/mTOR hyperactivation relative to Nf1+/+ (wild-type) astrocytes." (PMID 28380429, 2017). "Data suggest gartanin is a potentially effective anti‐viability agent against glioma, and this anti‐viability effect involves autophagy which is induced by inhibition of PI3K/Akt/mTOR pathway." (PMID 27491646, 2017). "CRNDE can promote the malignant progress of glioma by lessening miR-384/PIWIL4/STAT3 Axis, miR-186 or mTOR signaling pathways." (PMID 29088774, 2017).